MYCN (MYCN proto-oncogene, bHLH transcription factor)
Diseases named in the same sentence as MYCN in open-access papers (continued):
Sharing a sentence is not in itself a finding about the gene and the disease.
neuroblastoma (continued). "The neuroblastoma samples were previously evaluated for ATRX and DAXX mutations, and MYCN amplification." (PMID 38837897, 2024). "Using MYCN ChIP-seq data as well as qRT-PCR and reporter assays, we showed that TERT is a bona fide MYCN target in neuroblastoma cells." (PMID 38837897, 2024). "If the MYCN oncogene is amplified and the ALK oncogene acquires activating mutations in this lineage, the cells therein will become neuroblastoma cells and form a malignant solid tumour instead." (PMID 39715281, 2024). "Here we have determined that a core spliceosome protein, SNRPD3, plays a vital role in maintaining the fidelity and balance of MYCN-driven alternative splicing events which are required to promote neuroblastoma tumorigenesis." (PMID 38049564, 2024). "Immunoprecipitation identified fatty acid-binding protein 5 (FABP5) as an interaction partner of NBASP that had previously been already shown to be upregulated in MYCN-amplified neuroblastoma." (PMID 38891878, 2024). "EIF4G1 stood out as another interesting candidate driver in AML and lymphoid entities, supported by previous analyses suggesting that EIF4G1 is involved in cell survival in AML as a downstream target of MYCN, a known oncogene in neuroblastoma." (PMID 38769532, 2024). "MYCN amplifications are also found in around 25% of neuroblastomas, correlating with poor prognosis and representing a well-characterised and important clinical marker." (PMID 39682746, 2024). "Our findings highlight that disruption of SNRPD3 protein methylation using PRMT5 inhibitors is a promising novel therapeutic target for the treatment of high-risk neuroblastoma, particularly given the observed SNRPD3- and MYCN-selectivity." (PMID 38049564, 2024). "We validated this long-range interaction in several datasets, including in situ HiC data from primary cancer cell lines of MYCN-driven neuroblastoma, in which we can see a pronounced interaction." (PMID 39313745, 2024). "For example, concomitant FAK, Src and paxillin tumour positivity and myelocytomatosis oncogene (MYCN) amplification had statistically significant increased mortality in children with neuroblastoma." (PMID 39036223, 2024). "Since expression of FN1 has been linked to the mesenchymal state of neuroblastoma, we analyzed the transcriptome of the human stem cell-derived ALK/MYCN tumors." (PMID 38451815, 2024). "Together, our genetic interference and pharmacological inhibition data strongly suggest that PRMT5 is synthetically lethal with MYCN in neuroblastoma." (PMID 39313128, 2024). "We found that SNRPD3 ensures the fidelity and balance of MYCN-driven alternative splicing events required for neuroblastoma oncogenesis." (PMID 38049564, 2024). "Currently, the International Neuroblastoma Risk Group (INRG) classification system includes the following factors: disease stage, age at diagnosis, histological subgroup, tumor cell ploidy, MYCN status and 11q aberrations." (PMID 39796644, 2024). "Another study on neuroblastoma showed a similar effect of miR-2110 and the inverse expression of miR-2110 with MYCN mRNA levels." (PMID 38893174, 2024). "Together, these data suggest that SAGA loss of function can reduce cell cycle–related signatures through reduction of MYCN levels and altered binding on chromatin and suggest a potential mechanism to target MYCN-amplified neuroblastomas." (PMID 38820154, 2024). "At the molecular level, aggressive neuroblastoma tumor phenotypes correlate with a definite number of oncogene drivers, such as MYCN, ALK, and LIN28B." (PMID 38338881, 2024). "In the two virtual tumours with 25% of their initial neuroblastoma cell agents in their respective MYCN-amplified clones, the fractional composition went up to 25.2% at the end of each simulation." (PMID 39715281, 2024).
neuroblastoma (continued). "Dysregulation of MYCN is observed in various tumors in both pediatric and adult settings, encompassing neuroblastoma, Wilms’ tumor, rhabdomyosarcoma, lung cancer, medulloblastoma, retinoblastoma and basal cell carcinoma." (PMID 38884091, 2024). "Among the most enriched differential gene dependencies observed in MYCN-amplified neuroblastoma as compared to all other solid tumor lineages were TADA2B, TADA1, SUPT20H, and TAF5L, along with several other members of the core and KAT modules." (PMID 38820154, 2024). "MYCN-amplified neuroblastoma remains an aggressive childhood cancer with its core regulatory circuits less understood." (PMID 38992040, 2024). "Next, we sought to test the preclinical antitumor activity of rapamycin in vivo in mice harboring patient-derived xenograft models (PDX) of neuroblastomas with MYCN amplification." (PMID 38197697, 2024). "Here, we aimed to better understand the role of unsaturated fatty acid synthesis in pediatric neuroblastoma, a devastating disease in children that is driven by the MYC family member MYCN, where less than half of high-risk patients survive." (PMID 38672672, 2024). "MYCN amplification is the most frequent and predictive molecular aberration correlating with poor outcome in neuroblastoma." (PMID 38413795, 2024). "Alterations in MYC and CCND1 have been frequently observed in bladder cancer, correlating with aggressive phenotypes and worse prognosis, while MYCN alterations were most common in neuroblastomas." (PMID 39410541, 2024). "Here, we identify using ENU mutagenesis of Th-MYCN mice a pedigree harboring a single loss-of-function mutation in the co-repressor Runx1t1, which segregates with abolition of MYCN-driven neuroblastoma tumorigenesis." (PMID 38992040, 2024). "Tumors are histologically either undifferentiated or poorly differentiated neuroblastoma with a gene expression profile resembling late-stage MYCN-amplified disease." (PMID 38992040, 2024). "We established a human xenograft neuroblastoma tumor model by injecting MYCN-amplified IMR-32 cells into NCr nude mice." (PMID 38214542, 2024). "We further connected these disrupted patterns to MYCN and microRNAs, a special class of small RNAs important in neuroblastoma and other cancers." (PMID 38672672, 2024). "Samples were filtered to those with the required features (event-free survival (EFS), age at diagnosis, MYCN amplification and International Neuroblastoma Staging System (INSS) stage) and only genes present in all datasets were used (n = 35)." (PMID 38398114, 2024). "METTL3 knockdown or pharmacologic inhibition of the METTL3/14 complex with STM2457 decreased the proliferation of a panel of adrenergic neuroblastoma cells, including cells that harbored amplification of the MYCN oncogene." (PMID 38691450, 2024). "MYCNOS expression thus correlates positively with MYCN expression and, consequently, poor neuroblastoma outcomes." (PMID 38891878, 2024). "Here, we use the Cancer Dependency Map (DepMap) functional genomic screens to identify the lysine acetyltransferase (KAT) module of the Spt-Ada-Gcn5-acetyltransferase (SAGA) complex as an epigenetic regulator important for MYCN-amplified neuroblastoma growth." (PMID 38820154, 2024). "TRE-MYCN iPSC-derived neuroblastoma tumors aligned more closely with adrenergic than mesenchymal neuroblastoma, an observation consistent with MYCN-amplified human neuroblastoma cell lines." (PMID 38451815, 2024). "Mice homozygous for the MYCN transgene all develop neuroblastoma by 7 weeks of age8,9, making this an ideal model for an unbiased genetic suppressor screen using N-ethyl-N-nitrosourea (ENU) mutagenesis." (PMID 38992040, 2024). "Following the removal of batch effects, 2 clear clusters corresponding to MYCN-AMP and MYCN-normal neuroblastomas, respectively, were visualised using principal component analysis (PCA)." (PMID 38553589, 2024).
neuroblastoma (continued). "Firstly, MYCN amplification is well established in neuroblastoma accounting for 20%-30% of cases, but also observed in 25% of alveolar rhabdomyosarcoma cases, 5%-10% of medulloblastomas associated with poor prognosis." (PMID 38884091, 2024). "Together, these results support that the SAGA complex, as inferred by TADA2B binding, is predominantly colocalized with MYCN in the promoters of expressed and actively transcribed genes in MYCN-amplified neuroblastoma." (PMID 38820154, 2024). "To address this, we used tazemetostat for 3 weeks to inhibit EZH2 in two neuroblastoma cell lines with long telomeres containing doxycycline-inducible MYCN transgene (SKNMMMYCN and SKNJCIMYCN)." (PMID 38837897, 2024). "Overall, we detected a low level of enrichment for the repressive mark H3K27me3 in the majority of the MYCN-amplified neuroblastoma samples, with the exception of the O-PDX sample (SJNBL046) which displayed a relatively high level of H3K27me3." (PMID 38837897, 2024). "Recent work from our laboratory suggests AhR acts as a tumor promoter in MYCN-amplified neuroblastoma." (PMID 38807762, 2024). "Co-expression of MYCN and Bcl-2 genes has also been shown to induce the secretion and activation of matrix metalloproteinases in neuroblastoma, leading to the degradation of the extracellular matrix." (PMID 38959634, 2024). "Using matched cisplatin-sensitive KellyLuc and resistant KellyCis83Luc cell lines, we developed a cisplatin-resistant metastatic MYCN-amplified neuroblastoma model." (PMID 38809883, 2024). "In our previous study, we found that non–MYCN-amplified SK-N-AS neuroblastoma cells were significantly resistant to ZIKV permissivity and viral killing in vitro." (PMID 38214542, 2024). "As a result, MYCN overexpression leads to MALAT1 overexpression, constituting another lncRNA-mediated mechanism by which MYCN contributes to neuroblastoma tumorigenesis." (PMID 38891878, 2024). "We first confirmed that knockout (KO) of TADA2B using multiple independent sgRNAs impaired growth in three MYCN-amplified neuroblastoma models in low throughput." (PMID 38820154, 2024). "This classification is based on clinical features such as an age at diagnosis, chromosomal alterations, amplification of the MYCN oncogene, which occurs in approximately 20% of neuroblastomas, and distant metastatic disease." (PMID 38809883, 2024). "We picked neuroblastoma as a candidate since it has a strong dependence on MYCN and develop from fetal adrenal neuroblasts." (PMID 38411140, 2024). "DLG2 expression is negatively correlated with MYCN amplification and its location on chromosome 11q, a common chromosomal deletion in unfavourable neuroblastomas, further validates that it is a potential neuroblastoma prognostic biomarker." (PMID 38398114, 2024). "Using this approach, we identify and describe a role for the SAGA complex acetyltransferase activity in maintaining the oncogenic state in MYCN-amplified neuroblastoma." (PMID 38820154, 2024). "Using CRISPR/Cas9, LRP8 has been genetically deleted, resulting in the depletion of selenocysteine required for translation of anti-ferroptosis GPX4 and making MYCN-amplified neuroblastoma vulnerable to cell death." (PMID 38725484, 2024). "MYCN, a transcription factor in the MYC family, is known to be frequently amplified in neuroblastoma, causing an aggressive disease course." (PMID 39410541, 2024). "Consistent with the differential dependency analysis, we found that MYCN-amplified neuroblastoma cell lines are significantly more dependent on SAGA complex genes compared to all other solid tumor lineages." (PMID 38820154, 2024). "The study of MYCN expression in the neuroblastoma cells revealed a tendency to increase when cultured on biomaterials compared to plastic plates, although it was not statistically significant." (PMID 39872066, 2024).
neuroblastoma (continued). "For example, genomically amplified MYCN has been shown to drive global transcriptional amplification of active genes through binding with their promoters and enhancers in MYCN-amplified neuroblastoma." (PMID 38542080, 2024). "Altogether, these data provide evidence for recruitment by HAND2 of a RUNX1T1 repressor complex to help maintain an undifferentiated phenotype in MYCN-amplified neuroblastoma cells." (PMID 38992040, 2024). "Overall, this study has provided novel insights into the molecular mechanisms of SNRPD3 as an oncogenic protein, and alternative splicing in MYCN-driven neuroblastoma." (PMID 38049564, 2024). "MYCN has been found to promote tumor growth in a variety of cancers, including prostate cancer, breast cancer, and neuroblastoma." (PMID 39248163, 2024). "Our findings expand our understanding of the histone-modifying complexes that maintain the oncogenic transcriptional state in this disease and suggest therapeutic potential for inhibitors of SAGA KAT activity in MYCN-amplified neuroblastoma." (PMID 38820154, 2024). "Initially identified as a proto-oncogene amplified in neuroblastoma, MYCN amplification occurs in 20%-30% of neuroblastoma cases, serving as a critical prognostic marker associated with poorer outcomes." (PMID 38884091, 2024). "Notable DSGs included PKM, which has already been shown to undergo hnRNPA1-dependent alternative splicing in neuroblastoma and MLX, encoding a MYCN transcriptional co-activator regulating glutamine metabolism genes in neuroblastoma." (PMID 39313128, 2024). "For this we used the Th-MYCN mouse model for neuroblastoma, and an analogue of GSK3203591, namely GSK3326593, which has better characteristics for in vivo work." (PMID 39313128, 2024). "The aim of this study was to demonstrate the effectiveness of the FISH method for the evaluation of MYCN amplification on paraffin-embedded tissue sections and intraoperative tumor imprints together with HD SNP array analysis in neuroblastoma patients." (PMID 39049899, 2024). "Amplification of MYCN is frequently found in a number of advanced-stage tumours, including neuroblastoma (25%), small cell lung cancers (7%), alveolar rhabdomyosarcoma and retinoblastoma." (PMID 39867575, 2024). "MYCN is a transcription factor that induces transcriptional and epigenetic reprograming and MYCN-amplified neuroblastoma cells express TERT." (PMID 38837897, 2024). "The analysis revealed that PHLDA1 mRNA level positively correlates with event-free and overall survival of 92 neuroblastoma patients with MYCN-amplification." (PMID 38495105, 2024). "GLI1 is another promising biomarker, particularly for predicting neuroblastoma (NB) severity with high MYCN expression." (PMID 39568072, 2024). "To explore the association between mTORC1 pathway activation and the DDX1:DLST interaction, we ectopically overexpressed DDX1 or DDX1 Δ269-295aa in MYCN-amplified neuroblastoma cells." (PMID 38197697, 2024). "All 24 (100%) had stage 4 (or M) neuroblastoma at original diagnosis, and seven of 20 patients (35%) with available data had MYCN amplified tumors." (PMID 38200233, 2024). "Basal cysteine levels in neuroblastoma cells with amplified MYCN are relatively low, which is partly due to reduced cystine uptake via xCT and excessive usage of cysteine for protein synthesis." (PMID 38908072, 2024). "To assess neuroblastoma tumors with MYCN amplification we used paraffin-embedded tissue sections in 57 patients and intraoperative tumor imprints in 10 patients by fluorescence in situ hybridization (FISH)." (PMID 39049899, 2024). "To test both for a general requirement of each subunit in neuroblastoma cell proliferation and for MYCN-specific effects, we expressed each shRNA in SH-EP-MYCN-ER cell." (PMID 39177021, 2024). "We focused our efforts on identifying cooperating epigenetic complexes in MYCN-amplified neuroblastoma." (PMID 38820154, 2024).
neuroblastoma (continued). "Our recent study in MYCN-amplified neuroblastoma revealed that MP1 also targets MYCN (a MYC homologue) along with MCL-1, leading to autophagy stimulation and energy metabolism inhibition." (PMID 38200580, 2024). "We and others have also reported that AhR has a tumor suppressive role in non-MYCN-amplified neuroblastoma cells." (PMID 38807762, 2024). "For this reason, the metabolic profile of MYCN-amplified neuroblastomas has been widely studied, and its reprogramming has been defined as a possible vulnerability of this cancer." (PMID 38338881, 2024). "A growth dependence on EP300 has also been observed in high-risk pediatric neuroblastoma, with EP300 degradation resulting in loss of MYCN and subsequent cell death." (PMID 39766049, 2024). "Several studies have revealed that MYCN amplification, ATRX inactivation, and TERT promoter rearrangement are crucial molecular mechanisms that drive TMMs in high-risk neuroblastoma." (PMID 38891878, 2024). "It is documented that the microRNA-421 mediates downregulation of ATM gene via overexpression of MYCN transcriptional factor in neuroblastoma; however, this relation in pulmonary blastoma needs to be discovered through large cohort studies." (PMID 38235566, 2024). "Using immunoblotting, we confirmed strong AF1q expression in two MYCN amplified neuroblastoma lines (Kelly and Lan-5)." (PMID 38413795, 2024). "Even though pharmacologic mTOR inhibitors, such as rapamycin, are in clinical use in patients suffering from different cancers, including MYCN-amplified neuroblastoma, biomarkers predicting mTOR inhibitor sensitivity are largely lacking." (PMID 38197697, 2024). "In contrast to the MYCN-amplified neuroblastoma cells, the neuroblastoma samples with long telomeres, including cell lines, autopsies and O-PDX tumors, showed repressive chromatin marks, especially H3K27me3 in the same region of the proximal TERT promoter." (PMID 38837897, 2024). "Risk stratification is multifactorial, considering the International Neuroblastoma Risk Group (INRG) tumour stage, patient age at diagnosis, tumour histology, differentiation, MYCN status, DNA ploidy and chromosomal imbalances." (PMID 38809883, 2024). "BIX01294 and UNC0638, both G9a/GLP inhibitors, suppressed astrocytoma and neuroblastoma cell growth while increasing IFN-y-induced expression of CXCL10 mRNA in MYCN-amplified neuroblastoma." (PMID 39766049, 2024). "The amplification of MYCN, an oncogene located on chromosome 2p24–25, is one of the earliest discovered genetic markers of neuroblastoma and remains one of the strongest predictors of poor prognosis." (PMID 38891878, 2024). "In this work, we show that RUNX1T1 forms part of a repressive complex in neuroblastoma cells acting on enhancer regions to support MYCN and HAND2 in driving neuroblast hyperplasia and eventual transformation." (PMID 38992040, 2024). "All homozygote Th-MYCN+/+ transgenic mice develop neuroblastoma in the sympathetic ganglia at 6−7 weeks of age, after a precancer stage of neuroblast hyperplasia in the ganglia during the first 2 weeks of life." (PMID 38049564, 2024). "More importantly, we found that MYCN mRNA levels in neuroblastoma tumor specimens are positively and significantly correlated with CDKN3 mRNA levels in all the three independent patient datasets." (PMID 38356706, 2024). "Here, we identify that members of the core and KAT modules drive the selective dependency on the SAGA complex in MYCN-amplified neuroblastoma." (PMID 38820154, 2024). "Over the last 20 years, there has been little improvement in the overall survival of children with MYCN-amplified neuroblastoma." (PMID 38214542, 2024).